ADAMTS17 (ADAM metallopeptidase with thrombospondin type 1 motif 17)
Description:
Extracellular metalloprotease that regulates skeletal development by modulating BMP-SMAD signaling and extracellular matrix microfibril organization, which controls chondrocyte differentiation and bone growth.
Synonyms: FLJ32769; FLJ16363; WMS4
Tractability: Antibody: UniProt places it where antibodies can reach, with medium confidence; UniProt predicts a signal peptide or a membrane-spanning region; its Gene Ontology location is reachable by antibodies, with medium confidence. PROTAC: ubiquitination databases record sites on it.
Gene: Protein-coding gene on chromosome 15 (99,971,437 to 100,342,005, reverse strand). Ensembl gene ENSG00000140470.
Subcellular location: Secreted, extracellular space, extracellular matrix
Subcellular location (Human Protein Atlas): Nucleoplasm; Predicted to be secreted
Pathways (Reactome):
Disease: Defective B3GALTL causes PpS
Metabolism of proteins: O-glycosylation of TSR domain-containing proteins
Gene Ontology:
Molecular function: metalloendopeptidase activity; metallopeptidase activity
Biological process: extracellular matrix organization; proteolysis
Cellular component: extracellular matrix
Genetic constraint (gnomAD): Loss-of-function variants: 112 observed, 135.59 expected, observed/expected ratio (o/e) 0.83, 90% interval 0.71 to 0.97. The synonymous counts are far from expectation, so gnomAD's model fits this gene poorly and the ratio says little. Missense variants: 1,646 observed, 1,483.8 expected, observed/expected ratio (o/e) 1.11, 90% interval 1.06 to 1.15. Synonymous variants: 764 observed, 607.47 expected, observed/expected ratio (o/e) 1.26, 90% interval 1.18 to 1.34.
Homologues: Orthologues: chimpanzee ADAMTS17 (94% identical), dog ADAMTS17 (94% identical), pig ADAMTS17 (93% identical), macaque ADAMTS17 (90% identical), mouse Adamts17 (90% identical), rat Adamts17 (90% identical), rabbit ADAMTS17 (89% identical), guinea pig ADAMTS17 (88% identical), tropical clawed frog adamts17 (73% identical), zebrafish adamts17 (64% identical). Paralogues in human: ADAMTS19 (55% identical), ADAMTS12 (32% identical), ADAMTS7 (32% identical), ADAMTS18 (31% identical), ADAMTS20 (31% identical), ADAMTS9 (31% identical), ADAMTS16 (30% identical), ADAMTS6 (29% identical), ADAMTS10 (28% identical), ADAMTS2 (28% identical), ADAMTS14 (28% identical), ADAMTS15 (27% identical), and 13 more.
Diseases named in the same sentence as ADAMTS17 in open-access papers:
ADAMTS17 is named in the same sentence as 45 diseases in open-access papers, as found by Europe PMC text mining. Sharing a sentence is not in itself a finding about the gene and the disease. The quoted sentences say what the papers report.
glaucoma (17 papers, 2013 to 2025). Increased pressure in the eyeball due to obstruction of the outflow of aqueous humor. "Homozygosity of a glaucoma-causing canine ADAMTS17 variant was also associated with short stature in several dog breeds." (PMID 41034152, 2025). "A variant in ADAMTS17 confers a risk of glaucoma in Petit Basset Griffon Vendéen (PBGV) and Shar Pei but was also demonstrated to have an effect on height." (PMID 35205370, 2022). "Weill–Marchesani syndrome 4 (WMS4) is caused by ADAMTS17 gene variant and clinical abnormalities including lenticular myopia, ectopia lentis, glaucoma, microspherophakia, brachydactyly, and short stature." (PMID 36698805, 2022). "In humans, ADAMTS17 mutations are known to cause Weill-Marchesani-like syndrome, which is characterised by lenticular myopia, ectopia lentis, glaucoma, spherophakia, and short stature." (PMID 31131111, 2019). "Breed-specific homozygous mutations in ADAMTS17 are associated with primary open angle glaucoma (POAG) in several dog breeds, including the Petit Basset Griffon Vendeen (PBGV) and Shar Pei (SP)." (PMID 31131111, 2019). "Mutations in ADAMTS17 have also been identified in several dog breeds and are associated with inherited glaucoma and unstable lenses." (PMID 31131111, 2019). "Rare sequence variants in ADAMTS17 cause autosomal recessive Weill-Marchesani syndrome, a rare connective tissue disorder with features including microspherophakia, severe myopia, glaucoma, cataract, and short stature (OMIM: 607511)." (PMID 30894546, 2019). "Recessive mutations in the secreted metalloprotease ADAMTS17 cause ectopia lentis and short stature in humans with Weill-Marchesani-like syndrome and primary open angle glaucoma and ectopia lentis in dogs." (PMID 28176809, 2017). "In man, homozygous mutations in ADAMTSL4, ADAMTS10, ADAMTS17 cause various ocular phenotypes including ectopia lentis, myopia and glaucoma." (PMID 26474315, 2015). "The disease-associated interval contained 28 genes, including ADAMTS17, a potential glaucoma candidate gene." (PMID 26683476, 2015). "In dogs, mutations in ADAMTS10 and ADAMTS17 were associated with primary open angle glaucoma." (PMID 41034152, 2025). "Additionally, ADAMTS17 mutations have been implicated in short height and glaucoma in dogs and humans." (PMID 39575453, 2024). "In addition, an ADAMTS17 missense variant that causes primary lens luxation and primary open angle glaucoma in dogs has been reported." (PMID 36698805, 2022). "ADAMTS10 and ADAMTS17 both contribute to formation and function of fibrillin-1 microfibrils, leading us to form the hypothesis that microfibril defects can cause glaucoma." (PMID 30406200, 2018). "Homozygous mutations in the ADAMTS17 gene are known to cause Weill-Marchesani syndrome-4 (WMS4, OMIM: 613195), which is characterized by microspherophakia, severe myopia, glaucoma, cataract, brachydactyly, joint stiffness, and short stature." (PMID 36966180, 2023). "Mutations in ADAMTS10 and in ADAMTS17, which is genetically and functionally highly similar to ADAMTS10 cause glaucoma in dogs." (PMID 36148008, 2022). "From 21 glaucoma disease-associated genes with measurable expression, 2 were upregulated (MYOC and FOXE3) and five were downregulated (SH3PXD2B, NF1, SBF2, ADAMTS17, and FOXC1)." (PMID 35348588, 2022). "Involvement of ADAMTS10 with glaucoma has been verified in another dog breed and extended to include ADAMTS17 which is structurally and functionally highly similar to ADAMTS10." (PMID 36148008, 2022). "As genetic testing for the mutation in the ADAMTS10 and ADAMTS17 genes was not performed, the possibility of primary open-angle glaucoma in some of these cases cannot be excluded." (PMID 38444777, 2024).
ectopia lentis (10 papers, 2012 to 2024). "Mutations in ADAMTS10 and ADAMTS17 phenocopy mutations in ADAMTSL4 (ectopia lentis) and ADAMTSL2 (acromelic dysplasias), suggesting common functional pathways, and ADAMTSL3 also binds directly to ADAMTS10." (PMID 38324186, 2024). "Ectopia lentis is also caused by variants in FBN1, ADAMTS10, ADAMTS17 and LTBP2, suggesting a functional relationship in the regulation of zonule assembly." (PMID 38324186, 2024). "All the genes associated with ectopia lentis phenotypes to date, (ADAMTSL4, FBN1, LTBP2, ADAMTS10, ADAMTS17) included in the clinical exome employed, revealed several genetic variants in these genes." (PMID 29751740, 2018). "Mutations in ADAMTS17 cause WMS-like syndrome with ectopia lentis and ADAMTSL4 mutations cause isolated ectopia lentis and ectopia lentis et pupillae." (PMID 30060141, 2018). "These genetic studies strongly linked ADAMTS17 to FBN1 and implicated it in the formation of the ciliary zonule in the eye, the fibrillin-based structure defective in ectopia lentis, and in the regulation of skeletal growth." (PMID 28176809, 2017). "Mutations in ADAMTS17 cause a Weill-Marchesani-like syndrome, and mutations in ADAMTSL4 cause autosomal recessive isolated ectopia lentis." (PMID 22242013, 2012). "Autosomal recessive Weill–Marchesani (OMIM # 613195)—clinical features in this form can overlap autosomal-dominant Weill–Marchesani syndrome, but genes involved in the condition are: ADAMTS10, ADAMTS17, and LTBP2 (described in one family, without Ectopia Lentis)." (PMID 37443678, 2023).
Weill-Marchesani syndrome (8 papers, 2014 to 2024). Weill-Marchesani syndrome (WMS) is a rare condition characterized by short stature, brachydactyly, joint stiffness, and characteristic eye abnormalities including microspherophakia, ectopia of the lens, severe myopia, and glaucoma. "Mutations in ADAMTS17 are also linked to the Weill-Marchesani syndrome in humans, affecting connective tissue and leading to impaired vision, short stature, and musculoskeletal anomalies." (PMID 39575453, 2024). "ADAMTS10 and ADAMTS17 mutations give rise to Weill-Marchesani syndrome (WMS)-like spectrum and have been functionally associated with the assembly of fibrillin microfibrils." (PMID 33352066, 2020). "Mutations in human ADAMTS10 and ADAMTS17 cause Weill-Marchesani syndrome, which is characterized by short stature and eye abnormalities including microspherophakia (the lens of the eye is smaller than normal and spherically shaped)." (PMID 26994289, 2016). "Studies have observed that a catalytically inactive ADAMTS17 interferes with fibrillin-1 secretion, resulting in elastic fiber abnormalities and intracellular collagen accumulation in fibroblasts from patients with Weill-Marchesani syndrome." (PMID 39575453, 2024). "Mutations in ADAMTS10, ADAMTS17 and in fibrillin 1 (FBN1) have been associated with a Weill-Marchesani syndrome (WMS) (OMIM 277600)." (PMID 25372548, 2014).
Weill-Marchesani-like syndrome (7 papers, 2012 to 2025). "This has been observed in Weill-Marchesani-like syndrome, associated with recessive ADAMTS17 sporadic gene mutations." (PMID 40144770, 2025). "Genetic tests revealed homozygous compounds for ADAMTS17 responsible for Weill-Marchesani-like syndrome but a homozygous variant in GHS-R was also detected." (PMID 37443653, 2023). "Mutations in the ADAMTS17 gene in humans cause Weill-Marchesani-like syndrome, which is a connective tissue disorder." (PMID 31131111, 2019). "A Weill-Marchesani like syndrome (WMS) in humans was the first disease phenotype to be associated with mutations in the ADAMTS17 gene." (PMID 26683476, 2015). "Mutations in ADAMTS17 in humans cause Weill-Marchesani-like syndrome (WMLS)." (PMID 31131111, 2019). "Thirdly, ADAMTS17 mutations cause Weill-Marchesani and Weill-Marchesani-like syndromes in man." (PMID 26474315, 2015).
brachydactyly (5 papers, 2016 to 2022). A disease characterized by the presence of brachydactyly, including syndromic and non-syndromic forms. "An interesting correlation with published literature is that brachydactyly is uncommonly found among patients with pathogenic ADAMTS17 variants." (PMID 32616716, 2020). "Present evidence does not suggest any genotype-phenotype correlation when comparing the position of ADAMTS17 variants and the presence of brachydactyly, recognizing the limitations given the low number of reported cases." (PMID 32616716, 2020). "This may explain the common phenotypes of short height and brachydactyly in WMS4 caused by ADAMTS17 variants." (PMID 36698805, 2022). "This work expands understanding of the molecular pathogenesis of ADAMTS17, clarifies the variable hand phenotype, and underscores a role for anthropometrics in characterizing sub-clinical brachydactyly in these patients." (PMID 32616716, 2020). "This work expands our understanding of the molecular pathogenesis of ADAMTS17, clarifies the resultant hand phenotype, and underscores a role for anthropometrics in characterizing brachydactyly in these patients." (PMID 32616716, 2020). "The outcome of ADAMTS17 transcriptional suppression on fibrillin-2 assembly was akin to that ascribed to ADAMTSL2, which is mutated in geleophysic dysplasia, another short-stature-brachydactyly condition." (PMID 28176809, 2017).
acromelic dysplasia (3 papers, 2020 to 2024). "ADAMTS10, ADAMTS17 and, ADAMTSL2 are also involved in the pathogenic mechanism of acromelic dysplasia." (PMID 34912367, 2021).
carpal tunnel syndrome (2 papers, 2020 to 2026). Entrapment of the median nerve in the wrist that is characterized by numbness, tingling and painful movement. "ADAMTS10 and ADAMTS17 were identified in a genome-wide association study (GWAS) of more than 12,000 cases versus 390,000 controls as susceptibility loci likely to cause carpal tunnel syndrome." (PMID 32290605, 2020). "However, the possibility of studying double knockout mice for ADAMTS10 and ADAMTS17 may provide an opportunity to gain some insights into the contribution of these protease to multigenic traits, such as carpal tunnel syndrome or body fat distribution." (PMID 32290605, 2020). "These included associations with genes involved in neurotransmitter signaling (HTR3A), immune function (HLA-DQB1, BCL11A), extracellular matrix remodeling (COL11A1, ADAMTS17, LOXL4), axon guidance and neural development (DCC, ETV1, NEGR1), and carpal tunnel syndrome (DIRC3)." (PMID 41518141, 2026).
Peters plus syndrome (2 papers, 2017 to 2020). "Two of the overlapping genes ADAMTS17 and ADAMTSL4 participate in the pathway: Defective B3GALTL causes Peters-plus syndrome (PpS)." (PMID 32925905, 2020).
acute promyelocytic leukemia (1 paper, 2015). An aggressive form of acute myeloid leukemia (AML), characterized by arrest of leukocyte differentiation at the promyelocyte stage, due to a specific chromosomal translocation t(15;17) in myeloid cells. "There is one previous report of a gene rearrangement involving ADAMTS17 found in a patient with pregnancy-related acute promyelocytic leukemia." (PMID 26683476, 2015).
Arthritis (1 paper, 2013). Inflammation of a joint. "The ADAMTS family of genes is involved in cancer, arthritis and coagulation, and variants of ADAMTS17 are associated with pediatric stroke." (PMID 23874591, 2013).
autosomal recessive congenital ichthyosis 9 (1 paper, 2014). "Mutations in ADAMTS17 can cause autosomal recessive Weill-Marchesani-like syndrome [MIM 613195] while alteration of both ADAMTS17 and CERS3 have been associated with autosomal recessive congenital ichthyosis 9 (ARCI9) [MIM 615023]." (PMID 24860619, 2014).
breast carcinoma (1 paper, 2020). "Knocking down Adamts17 expression induces the apoptosis of breast cancer cells and inhibits cancer cell growth." (PMID 32596344, 2020).
cervical cancer (1 paper, 2023). A primary or metastatic malignant neoplasm involving the cervix. "Our review shows ADAMTS were found elevated in cervical cancer tissues, particularly ADAMTS17, which was associated with a poorer prognosis." (PMID 36982551, 2023).
chronic lymphocytic leukemia (1 paper, 2024). "For instance, analysis of differentially expressed and methylated genes shows the alterations of expression patterns and DNA methylation patterns of ADAMTS17, FMOD, and ZAP70 in chronic lymphocytic leukemia (CLL)." (PMID 38510251, 2024).
COVID-19 (1 paper, 2025). A disease caused by infection with severe acute respiratory syndrome coronavirus 2. "GWAS identified candidate genes common to both COVID-19 severity and PASC, including CNTNAP2, WWOX, and ADAMTS17, which are implicated in extracellular matrix remodeling and neurological and cognitive development." (PMID 41561974, 2025).
Hypercholesterolemia (1 paper, 2013). An increased concentration of cholesterol in the blood. "Among the DEGs that were down-regulated in common, between the hypertension only, and hypercholesterolemia plus sham groups (both vs. sham controls) were FOXN1, Ribosomal protein S3-like (LOC100354966) and ADAMTS17 (ADAM metallopeptidase with thrombospondin type 1 motif, 17)." (PMID 23874591, 2013).
Hypertension (1 paper, 2013). The presence of chronic increased pressure in the systemic arterial system. "Among the highly down-regulated genes in the MCA of the hypertension only group were FOXN1, ribosomal protein S3a-like and ADAMTS17." (PMID 23874591, 2013).
keratoconus (1 paper, 2023). A degenerative, structural disorder of the eye, characterized by a cone-shaped protrusion of the cornea. "Finally, we identified three genes, NOX4, FNDC3B, and ADAMTS17, present in regions of significant local covariance that also have known associations with both keratoconus and body height." (PMID 37561511, 2023).
Lens luxation (1 paper, 2015). Complete dislocation of the lens of the eye. "An ADAMTS17 splice donor site mutation has been associated with hereditary primary lens luxation in several breeds of dog." (PMID 26683476, 2015).
Marfan syndrome (1 paper, 2023). A disorder of the connective tissue. "Finally, we provided evidence that FBN1 is involved in normal IVD function by analyzing IVDs in patients with Marfan syndrome and suggested the potential role of ADAMTS17 in the AF of IVDs." (PMID 36966180, 2023).
mitral valve regurgitation (1 paper, 2025). "Pulmonary, aortic, and mitral valve stenosis, as well as mitral valve regurgitation have all been reported in patients with WMS, which could be exacerbated when ADAMTS10 and ADAMTS17 are both absent." (PMID 41034152, 2025).
osteoporosis (1 paper, 2015). A condition of reduced bone mass, with decreased cortical thickness and a decrease in the number and size of the trabeculae of cancellous bone (but normal chemical composition), resulting in increased fracture incidence. "Polymorphisms in ADAMTS genes have been associated with human diseases related with bone metabolism, including osteoporosis and OA, so ADAMTS17 could also be a potential gene implicated in CHD and secondary OA." (PMID 25874693, 2015).
cancer (5 papers, 2013 to 2022). A tumor composed of atypical neoplastic, often pleomorphic cells that invade other tissues. "Other cancer-related genes are ADAMTS17, LINC01748, LPAL2, SRP14-AS1 and WASH8P." (PMID 33672117, 2021).
connective tissue disorder (4 papers, 2010 to 2020). A disease involving the connective tissue. "Four members of the ADAMTS superfamily, ADAMTS10, ADAMTS17, ADAMTSL2 and ADAMTSL4 have been implicated in connective tissue disorders, including ADAMTSL2, the cause of GD." (PMID 20862248, 2010).
genetic diseases (2 papers, 2017 to 2022). "Determining the molecular mechanisms and substrates of orphan proteases, such as ADAMTS17, is crucial for understanding the pathogenesis of their associated genetic disorders." (PMID 28176809, 2017). "A few studies on ADAMTS-17 suggest that the occurrence of some genetic diseases may be related to mutations in ADAMTS-17." (PMID 35883515, 2022).
tumor (1 paper, 2022). "By contrast, expression of each of ADAMTS1, ADAM19, ADAMTS13, and ADAMTS17 in tumor tissue was 0.75-fold lower than that in NCL." (PMID 36230656, 2022).
ADAMTS17 also shares sentences with these, for which no sentence is quoted: Primary Open Angle Glaucoma (6 papers); Microspherophakia (4); myopia (4); depression (2); pancreatitis (2); schizophrenia (2); Acromicric dysplasia (1); autism (1); autosomal-recessive intellectual disability (1); Bicuspid aortic valve (1); geleophysic dysplasia (1); ichthyosis (1); infection (1); lens dislocation (1); mitral valve stenosis (1); musculoskeletal disorders (1); pulmonary valve stenosis (1); spondylosis (1); Traboulsi syndrome (1).